CITED2 (Cbp/p300 interacting transactivator with ED-rich tail 2)
Diseases named in the same sentence as CITED2 in open-access papers (continued):
Sharing a sentence is not in itself a finding about the gene and the disease.
CITED2 also shares sentences with these, for which no sentence is quoted: congenital heart malformation (4 papers); adenoma (2); atrial septal defect (2); Tetralogy of Fallot (2); abdominal aortic aneurysm (1); adrenal cancer (1); Autoimmunity (1); Coffin-Siris syndrome (1); connective tissue disorder (1); Glucose intolerance (1); Hashimoto thyroiditis (1); heart failure (1); hematological malignancies (1); Hyperglycemia (1); joint inflammation (1); kidney cancer (1); Leber congenital amaurosis 11 (1); leiomyoma (1); microcephalic osteodysplastic primordial dwarfism type II (1); microphthalmia (1); movement disorder (1); non-Hodgkin lymphoma (1); non-small cell lung carcinoma (1); osteosarcoma (1); Parkinson disease (1); progressive myoclonic epilepsy-10 (1); skeletal dysplasia (1); type 2 diabetes (1); undifferentiated pleomorphic sarcoma (1).